SOX4 (SRY-box transcription factor 4)
Description:
Transcriptional activator that binds with high affinity to the T-cell enhancer motif 5'-AACAAAG-3' motif. Required for IL17A-producing Vgamma2-positive gamma-delta T-cell maturation and development, via binding to regulator loci of RORC to modulate expression (By similarity). Involved in skeletal myoblast differentiation by promoting gene expression of CALD1.
Synonyms: CSS10; EVI16; IDDSDF
Tractability: PROTAC: ubiquitination databases record sites on it.
Gene: Protein-coding gene on chromosome 6 (21,593,751 to 21,598,619, forward strand). Ensembl gene ENSG00000124766.
Subcellular location: Nucleus
Subcellular location (Human Protein Atlas): Nucleoplasm; Mitochondria
Pathways (Reactome):
Signal Transduction: Deactivation of the beta-catenin transactivating complex
Gene Ontology:
Molecular function: DNA-binding transcription activator activity, RNA polymerase II-specific; DNA-binding transcription factor activity; protein binding; RNA polymerase II cis-regulatory region sequence-specific DNA binding; sequence-specific double-stranded DNA binding; DNA-binding transcription factor activity, RNA polymerase II-specific; transcription cis-regulatory region binding; DNA binding; miRNA binding
Biological process: negative regulation of myoblast differentiation; negative regulation of transcription by RNA polymerase II; positive regulation of apoptotic process; positive regulation of cell population proliferation; positive regulation of DNA-templated transcription; positive regulation of myoblast differentiation; positive regulation of transcription by RNA polymerase II; protein stabilization; regulation of DNA-templated transcription; ascending aorta morphogenesis; atrial septum primum morphogenesis; brain development; camera-type eye morphogenesis; cardiac right ventricle morphogenesis; cellular response to glucose stimulus; glial cell proliferation; glucose homeostasis; heart development; kidney morphogenesis; mesenchyme development; mitral valve morphogenesis; nervous system development; neuroepithelial cell differentiation; neuron differentiation; and 11 more
Cellular component: cytoplasm; nucleoplasm; nucleus; chromatin; transcription regulator complex
Genetic constraint (gnomAD): Loss-of-function variants: 1 observed, 6.59 expected, observed/expected ratio (o/e) 0.15, 90% interval 0.053 to 0.72. That is too few expected variants to judge how well the gene tolerates losing a copy. Missense variants: 662 observed, 582.79 expected, observed/expected ratio (o/e) 1.14, 90% interval 1.07 to 1.21. Synonymous variants: 465 observed, 296.16 expected, observed/expected ratio (o/e) 1.57, 90% interval 1.46 to 1.7.
Homologues: Orthologues: chimpanzee SOX4 (100% identical), macaque SOX4 (95% identical), pig SOX4 (95% identical), dog SOX4 (92% identical), mouse Sox4 (81% identical), rat Sox4 (81% identical), tropical clawed frog sox4 (61% identical), zebrafish sox4a (47% identical), zebrafish sox4b (47% identical), Drosophila melanogaster Sox14 (24% identical), Drosophila melanogaster Sox21a (15% identical), Drosophila melanogaster Sox102F (15% identical), and 1 more. Paralogues in human: SOX11 (39% identical), SOX12 (33% identical), SOX10 (19% identical), SOX7 (19% identical), SOX9 (18% identical), CFAP65 (18% identical), SOX17 (18% identical), SOX30 (17% identical), SOX6 (17% identical), SOX1 (17% identical), SOX8 (17% identical), SOX3 (16% identical), and 8 more.
Diseases named in the same sentence as SOX4 in open-access papers:
SOX4 is named in the same sentence as 212 diseases in open-access papers, as found by Europe PMC text mining. Sharing a sentence is not in itself a finding about the gene and the disease. The quoted sentences say what the papers report.
breast carcinoma (139 papers, 2008 to 2026). "SOX4 is an interesting transcription factor because it has been implicated in breast cancer Epithelial-Mesenchymal Transition (EMT), metastasis, and drug resistance in other tumors such as colon cancer." (PMID 36766786, 2023). "C-X-C motif chemokine ligand 1 (CXCL1), as a relatively specific biomarker of tumor-associated macrophages (TAMs), promotes breast cancer migration and invasion via NF-κB/SOX4 activation." (PMID 35443644, 2022). "As a member of this family, SOX4 is closely associated with both normal development and various cancers, such as lung cancer, breast cancer, leukemias, glioblastoma, and medulloblastoma." (PMID 36428735, 2022). "Taken together, these data show that loss of SOX4 leads to a strong impairment of primary tumor growth and metastatic outgrowth in a luminal breast cancer model." (PMID 34584219, 2021). "We propose that SOX4-mediated cell-cycle regulation is a major underlying aspect in human breast cancer development." (PMID 34584219, 2021). "For instance, CCL1 derived from tumor-associated macrophages promotes breast cancer metastasis through activating NF-κB/SOX4 signaling." (PMID 34108990, 2021). "In this study we have investigated the loss of SOX4 in mammary tumor development utilizing organoids derived from a PyMT genetic mouse model of breast cancer." (PMID 34584219, 2021). "Based on TCGA database and clinical specimens, we found that miR-30a expression is associated with a good prognosis whereas SOX4 is associated with a poor prognosis for breast cancer patients." (PMID 34234874, 2021). "In breast cancer the transcription factor SOX4 has been shown to be associated with poor survival, increased tumor size and metastasis formation." (PMID 34584219, 2021). "In this study, we purposed to investigate the role of SOX4 in the growth and metastasis in breast cancer and the underlying mechanism." (PMID 33005101, 2020). "Recent research indicates that CXCL1 from tumor-associated macrophages acts via downstream NFKB/SOX4 signaling in breast cancer." (PMID 33256011, 2020). "In breast cancer, SOX4 is directly controlled by miRNA-335, the loss of which is associated with disease progression and poor metastasis-free survival." (PMID 30507376, 2018). "In line with its increased metastasis-associated expression and role in EMT, depletion of SOX4 has also been shown to reduce metastasis formation in mouse models of breast cancer." (PMID 30507376, 2018). "It is demonstrated that an inhibition of SOX4 is associated with a decreased invasion and metastasis of breast cancer cells." (PMID 26377202, 2015). "Of note, SOX4 is a master regulator of the epithelial-mesenchymal transition (EMT) in breast cancer, and is associated with overexpression of LINC00340, a cis-acting element in cluster I (basal-related)." (PMID 25296969, 2014). "Elevation of SOX4 expression associated with repressed miR-129-2 or miR-335 is reported in gastric-, endometrial-, and breast cancers." (PMID 23251334, 2012). "In breast cancer, Sox2, Sox4, Sox9, and Sox10 may be associated with cancer stem cell properties and resistance to therapy." (PMID 40980324, 2025). "Similarly, in lung and breast cancers, high expression of SOX4 was associated with tumor aggressiveness and poor prognosis, and promoted tumor development by regulating the cell cycle, promoting cell proliferation and inhibiting apoptosis." (PMID 40644416, 2025). "Data from TMA verified that SOX4 expression was associated with poor prognosis in breast cancer." (PMID 34234874, 2021). "In mammary carcinoma and glioblastoma stem cells specifically SOX4 has been implicated as a regulator of SOX2, suggesting that the observed connectivity of this factor with PI3K/AKT signaling may also reflect an indirect regulatory circuitry further involving SOX2." (PMID 31477842, 2020).
breast carcinoma (continued). "Collectively, our findings reveal an apparent oncogenic function of TGFβ in promoting cell cycle progression and drug resistance through SOX4, highlighting the pro-tumorigenic role of TGFβ signaling in breast cancer progression." (PMID 41639049, 2026). "Validating the genome-wide analyses, we found that resistance of breast cancer cells to the CDK4/6 inhibitor palbociclib conferred by TGFβ stimulation was functionally dependent on SOX4." (PMID 41639049, 2026). "TRPM7 has already be shown to be involved in EMT of breast cancer cells by regulating calcium signaling and SOX4 transcription factor expression." (PMID 40274768, 2025). "For example, circDONSON promotes breast cancer cell proliferation and radioresistance through SOX4-mediated Wnt/β-catenin signaling, while other circRNAs, like circRNF10, exhibit tumor-suppressive properties." (PMID 40804731, 2025). "For example, in breast cancer, transcription factor SOX4 activates TGF-β signaling, promoting EMT, cancer progression, and eventually metastasis." (PMID 40507884, 2025). "In turn, MIR-191 suppresses the expression of a number of genes, including SOX4 in breast carcinoma." (PMID 39796785, 2025). "In a total of 462 studies examining gene abnormal expression involving over 20 cancer types, 23% of them identified abnormally high expression of SOX4 in cancers such as GC, melanoma, glioblastoma, lung cancer, and breast cancer." (PMID 39289763, 2024). "MiR-133a has emerged as a tumor suppressor in non-small cell lung cancer (NSCLC), esophageal cancer (EC), prostate cancer (PC) and breast cancer (BC), targeting genes such as SOX4, EGFR, FSCN1, and COL1A1." (PMID 38504785, 2024). "There is a report that AHR-mediated over expression of miR-212/132 cluster reduced migration and invasion of breast cancer cells by suppressing mRNA of pro-metastatic transcription factor SOX-4." (PMID 39125717, 2024). "TAMs-secreted CXCL1 mediates the EMT in breast cancer cells and induces the NF-κB-mediated expression of several metastatic genes, such as SRY-box transcription factor 4 (SOX4)." (PMID 38397187, 2024). "In breast cancer, CXCL1 originating from tumor-associated macrophages (TAMs) promotes tumor metastasis by activating signaling pathways such as NF-κB/SOX4." (PMID 38791448, 2024). "Similar clinical analyses about SOX4 in acute myeloid leukemia, breast cancer and bladder carcinoma have also been reported." (PMID 39052126, 2024). "CXCL1 can promote the migration and invasiveness of breast cancer by activating the transcription of SOX4 via the NF-κB pathway, resulting in the subsequent epithelial-mesenchymal transition (EMT) process." (PMID 38612764, 2024). "The tumor-associated macrophages-derived CXCL1 is involved in the regulation of breast cancer metastasis by activating the NF-κB/SOX4 pathway." (PMID 36614235, 2023). "SOX4 assumes a carcinogenic role in prostate, bladder, and breast cancers by fostering cancer cell proliferation, migration, and invasion." (PMID 36987665, 2023). "Compared with the adjacent normal tissues, the protein expression of SOX4 was markedly increased in breast cancer, LUAD, and UCEC." (PMID 37958409, 2023). "This is consistent with findings in other models, including a breast cancer cell line and a melanoma cell line where miR-129-5p targets SOX4." (PMID 37375678, 2023). "Studies from breast cancer cells showed that SOX4 is a downstream of Transforming growth factor beta (TGFβ) signaling and that SOX4 expression was required for TGFβ-mediated induction of a subset of SMAD3/SOX4-co-bound genes." (PMID 35529852, 2022). "SOX4 increases breast cancer cell viability, migration, and invasion in vitro, and enhances tumor growth and metastasis in vivo." (PMID 36077333, 2022). "Studies also show that SOX4 regulates cell survival and metastasis of cancer cells, such as breast cancer." (PMID 36428735, 2022). "SOX4 protein expression correlates with tumor size, mitotic index and poor prognosis of breast cancer patients." (PMID 34584219, 2021).
breast carcinoma (continued). "In order to identify cell lines for in vitro studies, we used data from publicly available gene expression and proteome profiling studies to examine SOX4 mRNA and protein expression in a panel of breast-cancer cell lines." (PMID 33837205, 2021). "An earlier study also showed that miR-191-5p increased the doxorubicin sensitivity by targeting SOX4 in breast cancer cells." (PMID 34258391, 2021). "SOX4 contributed to cell growth and metastasis in breast cancer in vitro and in vivo by binding to the CXCR7 promoter to enhance its transcription." (PMID 33854048, 2021). "The SOX4-overexpressing ovarian, lung, gastric, liver, and breast cancer cells were established by lentivirus gene delivery system." (PMID 33482915, 2021). "The expression level of Snail, Sox4, and Twist1 was significantly decreased in miR-381-3p-overexpressed breast cancer cells." (PMID 34362391, 2021). "LINC01133 inhibits breast cancer invasion and metastasis through repressing SOX4 expression by recruiting EZH2 to SOX4 promoter." (PMID 33834618, 2021). "Up to now the role of SOX4 in breast cancer has been studied in cell lines consisting of untransformed epithelial cells or in basal/mesenchymal-like tumor cells." (PMID 34584219, 2021). "SOX4 was also observed to be a target of miR-129-5p in breast cancer, esophageal carcinoma, chondrosarcoma or cervical cancer, in which miR-129-5p mediated repression of SOX4 was associated with reduced cancer cell progression." (PMID 34063443, 2021). "Previous studies showed that amplification of SOX4 modulates PI3K-AKT signaling in breast cancer by regulating AKT phosphorylation." (PMID 33824274, 2021). "MiR-335 suppresses metastasis and migration by targeting the progenitor cell transcription factor SOX4 and has been identified as a metastasis suppressor miRNA in human breast cancer." (PMID 33470407, 2021). "Based on these analyses, as well as previously published PI3K activity scores, HCC1143 and HCC1954 were identified as basal-like breast-cancer cell lines with high SOX4 expression and high PI3K activity and selected for in vitro studies." (PMID 33837205, 2021). "In the CPTAC dataset, protein expression of SOX4 was highly increased in breast cancer, uterine corpus cancer, and lung cancer." (PMID 34442467, 2021). "In breast cancer, SOX4 is elevated and induces epithelial–mesenchymal transition (EMT) and metastasis." (PMID 34945712, 2021). "At present, some scholars have found the abnormal expression of SOX4 in many kinds of human malignant tumors, such as breast cancer, bladder cancer, ovarian cancer, colorectal cancer, prostate cancer, hematological malignant tumor and so on." (PMID 34496348, 2021). "More and more studies have shown that SOX4 can participate in the development of malignant cancers such as breast cancer and gastric cancer by affecting cell growth, metastasis, and apoptosis." (PMID 34249089, 2021). "We compiled ranked lists of genes based on their co-expression with SOX4 in human breast cancers in the TCGA and METABRIC studies." (PMID 34584219, 2021). "Here we have interrogated the role of SOX4 in breast cancer using organoids derived from a MMTV-PyMT; MMTV-Cre; Ecadherin-mCFP mouse model." (PMID 34584219, 2021). "In glioblastoma reduced expression of SOX4 abrogates tumorigenic activity and in breast cancer, SOX4 overexpression positively correlates with tumor grade and promotes metastasis." (PMID 34945712, 2021). "For example, previous studies have confirmed that PRC2 methyltransferase Enhancer of Zeste Homolog 2 (EZH2) positively regulates breast cancer cell EMT through interaction with SOX4." (PMID 34943943, 2021). "In the current study, we identified a novel mechanism by which SOX4 regulates PI3K signaling in basal-like breast cancer." (PMID 33837205, 2021). "Together, this study uncovers a novel mechanism by which SOX4 regulates a progenitor cell cycle program that is crucial for propagation in breast cancer." (PMID 34584219, 2021).
breast carcinoma (continued). "Using a combination of proteomics-based kinome profiling, transcriptomic analyses and molecular approaches, we identified TGFBR2 as a critical downstream target of SOX4 in basal-like breast-cancer cell lines." (PMID 33837205, 2021). "Taken together, these data suggest that SOX4 is required to maintain PyMT mammary tumor cells in an undifferentiated state." (PMID 34584219, 2021). "Taken together, these data suggest that SOX4 is required for maintenance of a progenitor-like gene expression program that stimulates cell cycle progression in mammary tumors." (PMID 34584219, 2021). "Our findings suggest that SOX4 expression in mammary tumors leads to re-activation of such developmental gene programs." (PMID 34584219, 2021). "Our data suggests that SOX4 regulates mammary tumor growth in the PyMT model independently of promoting EMT." (PMID 34584219, 2021). "Our study identifies a novel role for SOX4 in maintaining mammary tumors in an undifferentiated and proliferative state." (PMID 34584219, 2021). "To explore how SOX4 affects mammary tumor progression in this model, we generated SOX4 knockout organoid lines (SOX4KO)." (PMID 34584219, 2021). "The protein expression levels of SOX4 in breast cancer cell lines SUM149, MDA-MB-231, and BT474 were variable, low in SUM149 and MDA-MB-231 and high in BT474 by Western blot." (PMID 33005101, 2020). "After CXCL1 treatment, SOX4 expression significantly increases in the nucleus of various breast cancer cell lines." (PMID 33123472, 2020). "We studied the effect of SOX4 on migration and invasion of breast cancer cells using Transwell migration assay and Matrigel invasion assay, respectively." (PMID 33005101, 2020). "A large body of researches have illustrated that SOX4 exert oncogenic function in various cancers, such as squamous cell carcinoma, melanoma and breast cancer." (PMID 31894841, 2020). "Treatment of breast cancer cells with the CXCR7 inhibitor CCX771 reversed the SOX4 effect on cell migration and invasion." (PMID 33005101, 2020). "SOX4 increased breast cancer cell viability, migration, and invasion in vitro and enhanced tumor growth and metastasis in vivo." (PMID 33005101, 2020). "In this study, we demonstrated that SOX4 promotes the growth and metastasis of breast cancer both in vitro and in vivo." (PMID 33005101, 2020). "SOX4 positively regulates the endothelin-1 expression and facilitates endothelin-1 secretion in breast cancer." (PMID 33123472, 2020). "To explore the potential role of SOX4 in breast cancer treatment, we investigated its effect on cancer cell resistance to several commonly used chemotherapeutic agents including ecarboplatin, adriamycin, 5-fluorouracil, and paclitaxel." (PMID 33005101, 2020). "Taken together, our results indicated that LINC01133 inhibits breast cancer progression at least in part through suppressing SOX4." (PMID 31557401, 2019). "Mechanism investigations furthered identified the NF-κB/SOX4 signaling as the major target of TAMs/CXCL1 in promoting breast cancer metastasis." (PMID 31803057, 2019). "Here, for the first time, we showed that LINC01133 exerted anti‐oncogenic functions in breast cancer cells by inhibition of SOX4." (PMID 31557401, 2019). "In breast cancer, SOX4 is believed to play a critical role in the early stages of the malignant progression of breast cancer." (PMID 30072631, 2018). "High levels of SOX4 gene expression have been reported in diverse human cancers including leukemia, colorectal cancer, lung cancer and breast cancer." (PMID 30072631, 2018). "To further study the role of SOX4 in tumor-induced angiogenesis in vivo, we made use of a xenograft mouse model of breast cancer, in which MDA-MB-231 cells are transplanted into the mammary fat-pad of immune-deficient mice." (PMID 30507376, 2018).